MTOR (mechanistic target of rapamycin kinase)
Diseases named in the same sentence as MTOR in open-access papers (continued):
Sharing a sentence is not in itself a finding about the gene and the disease.
cancer (continued). "Studies also report that mTOR activity is altered in a wide range of pathological states, such as cancer, cardiovascular diseases, and neurodegenerative disorders." (PMID 30032425, 2019). "Nanoparticle-based mTOR targeted therapy proposes an attractive therapeutic option for various types of cancers." (PMID 30642006, 2019). "Migration and invasion of trophoblast cells play a crucial role in placentation, and downregulation of AKT/mTOR signaling has been correlated with cancer cell migration and invasion." (PMID 31316078, 2019). "CTC inhibited the survival and proliferation of diverse cancer cells as well as down-regulated Akt/mTOR signaling pathway and suppressed various proteins involved in anti-apoptosis, metastasis, and angiogenesis." (PMID 30813295, 2019). "A pan-cancer multi-omic integrative study correlated miR-21-3p levels with TSC2 expression, mTOR pathway activation, and a predictive signature for mTOR inhibitor-sensitivity in PPGLs and other cancers." (PMID 31410193, 2019). "PI3K/Akt/mTOR signaling pathway is a classical pathway, which not only promotes angiogenesis and cell progress, but also plays an important role in various human malignant tumors." (PMID 31340526, 2019). "The mTOR inhibitors, called “rapalogs,” used as anti-cancer drugs belonged to a class of rapamycin derivatives." (PMID 30987378, 2019). "Previously, it has been noted that mTOR is involved in regulating cell adhesion in cancer cells; however, the mechanistic pathway downstream of mTOR has not been explored." (PMID 31555280, 2019). "While PI3K/Akt/mTOR can be considered as a stress-dependent overlapped pathway between AD and cancer, future studies are still required to elucidate the further details, linking stress-related hormones to PI3K/Akt/mTOR dysregulation." (PMID 30881282, 2019). "A recent study analysing The Cancer Genome Atlas (TCGA) pan-cancer cohort looked in detail at molecular alterations involving the PI3K/AKT/mTOR pathway." (PMID 35582282, 2019). "Several genomic alterations in HNSCC affect the PI3K/AKT/mTOR pathway activation, which plays an important role in cancer initiation and progression." (PMID 31905951, 2019). "Other studies have also shown that CBD induces apoptosis via inhibition of Akt/mTOR pathway and this relates to the fact that Akt is overexpressed in many human cancers and is responsible for their resistance to apoptosis." (PMID 30713602, 2019). "Dysregulation of the class I PI3K-Akt-mTOR pathway is the one of most common mechanisms responsible for the development of various types of human cancers." (PMID 30902093, 2019). "In the cancer patient samples, it was shown that activated Akt promotes protein synthesis in cancer cells through mTOR complex." (PMID 30717410, 2019). "They further raise the possibility of targeting the PI3K/mTOR axis as a promising therapeutic approach in HH driven cancers that are resistant to SMO inhibitors." (PMID 31492956, 2019). "Such resistance to mTOR inhibition underscores how the metabolic plasticity of cancer cells enables the emergence of alternative mechanisms to feed the growing tumor." (PMID 31817676, 2019). "It appears that mTOR inhibitors have mixed efficacy in patients with distinct kinds of cancer and among patients with the same kind of cancer." (PMID 31277692, 2019). "In cancer cells, aberrant expression of PI3K/Akt/mTOR signaling pathway has been associated with enhanced metabolic activities including enhanced uptake of nutrients such as glucose, amino acid." (PMID 30875788, 2019). "Given that mTOR has critical roles in tumor progression, mTOR inhibitors hold promise in cancer therapy." (PMID 31277692, 2019). "In this perspective, different genes were identified that by activating the mTOR pathway, behave like oncogenes that promote cellular mass growth in cancer and senescence." (PMID 31174250, 2019).
cancer (continued). "The result was supported by a previous finding that compound C induces autophagy in cancer cells through blockade of mTOR pathways." (PMID 31121855, 2019). "Activation of the PI3K/AKT/mTOR pathway contributes to the resistance to anti-cancer agents, including microtubule-targeting agents." (PMID 31480338, 2019). "Above studies have shown mTOR pathway is crucial for regulation of tumor growth and sensitivities to anti-cancer drugs in CCA." (PMID 30682771, 2019). "A mechanism of resistance to mTOR inhibition in cancer is the rapalog-mediated activation of upstream PI3K/AKT and MAPK/ERK signaling." (PMID 31388935, 2019). "Aberrant mTOR signaling resulting from genetic alterations from different levels of the signal cascade is commonly observed in various types of cancers." (PMID 30754640, 2019). "The phosphoinositide 3‐kinase (PI3K), AKT (also known as protein kinase B, PKB) and mammalian target of rapamycin (mTOR), dominate various indications of cancer including cell cycle, survival, metabolism, motility, and genomic instability." (PMID 30523643, 2019). "All in all, we demonstrate for the first time that EOC chemoresistance is associated with PI3K/Akt/mTOR signaling, EMT, and CSCs, which contributes to cancer cell survival, migration, and invasion." (PMID 31234823, 2019). "The PTEN mutational status affects the response to combined therapy based on MEK and mTOR inhibitors in cancer, a fact that needs to be further investigated in the context of personalized treatment." (PMID 31652660, 2019). "The dysregulation of mTOR has been observed in many diseases like cancer, diabetes, neurodegenerative disorders, and aging." (PMID 31649622, 2019). "AKT/mTOR signaling pathway, which is a crucial regulator of cellular processes in response to environmental cues, controls the glycolytic metabolism in cancer and other cells." (PMID 30770822, 2019). "Consistent with this, cancer evolution inhibits the mTOR pathway, as shown here in the W group, and these results support decreased protein synthesis, increased protein degradation, and reduced muscle weight." (PMID 31200474, 2019). "As we know, the PI3K/Akt/mTOR signaling pathway plays an important role on migration, invasion, and proliferation of malignant tumors." (PMID 30870998, 2019). "In sum, this analysis shows that INCISOR successfully predicts genetic interactions (of mTOR) whose functional activation in cancer cells increases cellular fitness." (PMID 30858180, 2019). "Hyperactivation of the phosphatidylinositol 3-kinase (PI3K)/mammalian target of rapamycin (mTOR) signaling pathway has been observed in a high percentage of human cancers inducing growth, survival, and proliferation." (PMID 31752127, 2019). "The Akt/mTOR pathway has been reported to be frequently deregulated in human cancers, regulating the apoptotic response through its ability to interact with a number of key players in the apoptotic process." (PMID 30813295, 2019). "In conclusion, mTOR signaling pathway connecting with several other pathways and networks regulates cancer proliferation and progression." (PMID 30682771, 2019). "Collectively, these results indicate that activation of the pro-survival Akt and mTOR signaling pathways can eventually increase the DNA-repair capacity of repeatedly irradiated cancer cells and thereby promote the acquisition of radioresistance." (PMID 31799186, 2019). "The unrestricted proliferative potential of cancer cells is closely dependent on PI3K/AKT/mTOR signaling pathway." (PMID 30857125, 2019). "The phosphatidylinositol 3-kinase (PI3K)/AKT/mammalian target of rapamycin (mTOR) pathway is activated in many human cancers." (PMID 31178979, 2019). "The suppression of the Akt/mTOR signaling has been shown to be an effective strategy to the treatment of cancers and is the mechanism for the activity of many anti-tumor agents." (PMID 31889892, 2019).
cancer (continued). "Lastly, we discuss recent innovative strategies in manipulating the tumor microenvironment using mTOR inhibitors to target the growing tumor or to improve immunotherapy for cancer treatment." (PMID 31817676, 2019). "Activation of the PI3K/AKT/mTOR pathway promotes cancer progression and resistance to endocrine therapy." (PMID 31889900, 2019). "As the PI3K/Akt/mTOR signaling pathway plays a pivotal role in GB survival, inhibiting this pathway using anti-cancer natural polyphenols offers a viable strategy to prevent GB growth." (PMID 31841506, 2019). "Here we discuss the possible involvement of the PI3K/Akt/mTOR pathway as one of the triggers in the pathophysiology of cancer and AD, in relation to cell cycle." (PMID 30881282, 2019). "Activation of mTOR signaling initiates metabolic symbiosis in cancer cells, which confers resistance to VEGF inhibitors." (PMID 30927928, 2019). "Given the key role of the mTOR pathway in cell growth, regulation of actin cytoskeleton, gene transcription, ribosome biogenesis, and mRNA translation, there appears to be a link between mTOR activation and cancer." (PMID 31849319, 2019). "In conclusion, deregulation of cell cycle as a result of PI3K/Akt/mTOR pathway activation can be considered as a trigger for neurodegeneration in AD and explains the overlapped pathogenesis between AD and cancer with a diverse destiny." (PMID 30881282, 2019). "This review highlights recent advances in understanding the role or regulation of mTOR in cancer therapy." (PMID 31075885, 2019). "Cancer cells that acquire cisplatin resistance lack apoptotic capacity with frequently observed abnormal activation of the Akt/mTOR pathway." (PMID 31387554, 2019). "CDC25B is known to be able to activate the serine/threonine kinase AKT in cancer cells treated with the mTOR inhibitor, rapamycin." (PMID 31024841, 2019). "The PI3K/AKT/mTOR pathway is altered in cancer and activated in autophagy and for overcoming apoptosis in cancer cells." (PMID 30280445, 2019). "The PI3K/Akt/mTOR signaling pathway is often deregulated in cancers, modulating cell growth, apoptosis, malignant transformation, tumor progression and metastasis." (PMID 30791886, 2019). "The PI3K/AKT/MTOR axis is one the most frequently altered pathways in human tumors and directly participates in the regulation of many cancer hallmarks." (PMID 31007884, 2019). "Phosphatidylinositol-3-kinase (PI3K)/AKT/mammalian target of rapamycin (mTOR) signaling is one of the most important intracellular pathways, which can be considered as a master regulator for cancer." (PMID 30782187, 2019). "As one of the most important intracellular signaling pathways, the Phosphoinositide-3-Kinase (PI3K)/mammalian target of rapamycin (mTOR) pathway is frequently altered in human cancers, including HCC." (PMID 30975125, 2019). "Further studies showed that GOLPH3 promotes the development of cancer by activating mammalian target of rapamycin (mTOR) signaling, enhancing AKT activity, and decreasing forkhead box O1 (FOXO1) transcriptional activity." (PMID 31737112, 2019). "Adiponectin, by its receptors ADIPOR1 and ADIPOR2, blocks pro-cancer effects of mTOR and, in particular, prevents angiogenesis." (PMID 31443386, 2019). "The pathological relevance of dysregulation of mTOR signal is illustrated in many human diseases, especially the multitude of different human cancers." (PMID 30754640, 2019). "PI3K/Akt/mTOR signaling is important in cell survival and is involved in the resistance to many cancer therapies, including RTK inhibitors." (PMID 31262325, 2019). "It has been well-documented that autophagy and the PI3K/AKT/mTOR pathway play pivotal regulatory roles in tumorigenesis and cancer therapy, as well as becoming therapeutic targets for many anticancer drugs." (PMID 31835352, 2019).
cancer (continued). "eIF4F assembly falls under the governance of the PI3K/mTOR pathway, a signalling cascade usurped in the majority of human cancers - making it an attractive target for therapeutic development." (PMID 30718665, 2019). "For example, at physiological concentrations, EGCG is an ATP-competitive inhibitor of both PI3K and mammalian target of rapamycin (mTOR); thus, exerting its anti-cancer effect by inhibiting Akt phosphorylation and cell proliferation." (PMID 30893904, 2019). "Activation of autophagy in mature cancer cells promotes malignant behavior, and conflicts with the effects of inhibition of the PI3K/AKT/mTOR pathway on cancer cells." (PMID 31835352, 2019). "Another interaction with the mTOR pathway that leads to cell death is the inhibition of the aerobic glycolysis in anaerobic conditions (Warburg effect), which is promoted in cancer cells by the HIF1α pathway." (PMID 31013694, 2019). "It has been reported that brevilin A inhibits the PI3K/AKT/mTOR pathway to induce apoptosis and autophagy in many cancers." (PMID 31178739, 2019). "PI3K/mTOR signaling components have been prime targets for the development of anti-cancer agents in past years." (PMID 31752127, 2019). "Therapies utilizing mTOR inhibitors have been developed to reduce the high mTOR signaling levels in various cancer types." (PMID 30754640, 2019). "For example, drugs that target the PI3K/Akt/mTOR pathway have shown activity in a range of cancers, including renal cell carcinoma and triple-negative breast cancer (TNBC), where conventional anti-cancer therapies have failed." (PMID 31227862, 2019). "Hyperactivation of the mTOR pathway occurs in majority of the cancers, which results in increased eIF4E activity." (PMID 31586263, 2019). "Taken together, our results further support that PC1 interacts with the mTOR pathway in cancer cells." (PMID 31251475, 2019). "This suggests that this population of cancer cells utilizes mTOR signaling to contribute to the survival and pathogenicity of human cancers." (PMID 31288154, 2019). "In their pan-cancer analyses, the authors reported 2% mutation rate in TSC1 and 4% mutation rate in mTOR." (PMID 35582282, 2019). "Consistently, everolimus, a mTOR inhibitor, exhibited significantly higher anti-tumor activities in ECs compared with other cancer types." (PMID 31771620, 2019). "The therapeutic development of mTOR inhibitors has improved due to their importance in cancer progression and development." (PMID 31075885, 2019). "Activation of PI3K/AKT and mTOR pathways is the main development mechanism in many types of cancer, therefore their inhibitors are a promising target in the search for new treatment strategies." (PMID 30848427, 2019). "Transgenic mice carrying additional copies of Pten, the negative regulator of PI3K/AKT/mTOR pathway, were observed to live longer and have lower incidence of cancer relative to normal." (PMID 31200451, 2019). "Metabolic (mTOR) activity, an essential feature of (cancer) cell biology that is particularly relevant with a view to drug sensitivity testing, was found to be increased in the tissue slices when cultured ex vivo, as has been reported by others." (PMID 30765891, 2019). "The mTOR signaling pathway, which is a key regulator of protein synthesis, is unusually active in many cancers and autoinflammatory and autoimmune diseases." (PMID 31137815, 2019). "Especially, a number of miRNAs have been identified to directly target components of the mTOR signaling pathway, because deregulation of multiple elements of the mTOR signaling pathway has been reported in many types of cancers." (PMID 30518907, 2019). "Downregulated genes of siAKT group were enriched in a total of 18 various cancer pathways, such as central carbon metabolism in cancer, apoptosis, and mTOR signaling pathway." (PMID 31781484, 2019). "Recently, it was reported that loss of miR-204 resulted in BDNF/TrkB overexpression and activation of the AKT/mTOR/Rac1 signaling pathway in cancer cells." (PMID 31480771, 2019).
cancer (continued). "The rapalogs and catalytic mTOR inhibitors were useful in immunosuppression in a small number of cancers." (PMID 30987378, 2019). "In this review, we discuss the roles of mTOR in human cancer and the rationales and challenges for developing mTOR inhibitors to treat cancer." (PMID 31277692, 2019). "Over the past few years, it has been extensively demonstrated in animal models and clinical patients of cancer that mTOR dysfunction contributes to tumorigenesis." (PMID 30754640, 2019). "mTOR inhibition was found to exert antitumor activity in this cancer subtype in preclinical studies." (PMID 31569540, 2019). "The mitogen-activated protein kinase (MAPK) pathway and the pPI3K/Akt/mTOR pathway have emerged as crucial signaling cascades involved in regulating cell growth, proliferation, and cell death in various cancers." (PMID 30959969, 2019). "In spite of having high ability in inhibiting the activity of mTOR, inhibitors are quite inadequate in fighting against cancer." (PMID 31030499, 2019). "The use of mTOR inhibitors for the improvement of vaccination strategies also promises to have a major impact towards cancer vaccination." (PMID 31817676, 2019). "SBI-0206965 enhances apoptosis in cancer cells through the diminishing of autophagy following mTOR inhibition." (PMID 31557936, 2019). "As registered in clinicaltrials.gov, there are more than 80 clinical trials for mTOR inhibitor monotherapy in cancer patients." (PMID 31277692, 2019). "Blocking of mTOR activity was shown to augment shuttling of pyruvate into gluconeogenesis, which results in futile cycling of glucose that finally leads to a halt in cancer cell proliferation and ultimately to cell death." (PMID 31484429, 2019). "mTOR signaling is the second most frequently altered pathway in human cancers, and most drugs are able to induce autophagy by blocking the mTOR pathway." (PMID 31569540, 2019). "Calorie or glucose restriction (CR or GR) inhibits energy-dependent pathways, including IGF-1/PI3K/Akt/mTOR, in cancer cells." (PMID 31091659, 2019). "RICTOR (rapamycin‐insensitive companion of mTOR) has been found to be overexpressed in various cancers (e.g., gastric and lung) and to be capable of cooperating with other driver mutations to stimulate cellular proliferation." (PMID 31393061, 2019). "Inhibition of mTOR using rapamycin increases cytotoxicity of Vγ4 γδ T cells towards various cancer cell lines by enhancing NKG2D expression and TNF-α expression." (PMID 31817676, 2019). "RSV is an attractive candidate for cancer therapy because of its unique capacity to affect the mTOR/AMPK pathway at different levels." (PMID 31324056, 2019). "Chlorpromazine (CPZ), a dopamine D2 receptor antagonist, is able to cross the cell membrane and bind to FKBP-12, inhibiting the mTOR pathway, one of the most frequent points of dysregulation in cancer." (PMID 31480389, 2019). "Among these enriched pathways, many are tumour‐related, such as MAPK signalling pathway, PI3K‐Akt signalling pathway, pathways in cancer, microRNAs in cancer, mTOR signalling pathway and Ras signalling pathway." (PMID 31613058, 2019). "These include the mammalian target of rapamycin (mTOR), a serine/threonine kinase that has a key role in cancer, promoting cellular activities that include protein synthesis, autophagy, survival, proliferation and growth." (PMID 30974835, 2019). "The AKT/mTOR signaling pathway is important for regulating cell proliferation, cancer growth and longevity." (PMID 31452776, 2019). "The de-regulated activity of mTOR is involved in many pathophysiological conditions, such as aging, Alzheimer’s disease, diabetes, obesity, and cancer." (PMID 31277692, 2019). "mTOR inhibition has shown beneficial effects in the setting of organ transplantation, cancer, and senescence, but the inhibition of mTOR can also lead to serious side effects." (PMID 31354486, 2019).